MAP2K5 (mitogen-activated protein kinase kinase 5)
Description:
Acts as a scaffold for the formation of a ternary MAP3K2/MAP3K3-MAP3K5-MAPK7 signaling complex. Activation of this pathway appears to play a critical role in protecting cells from stress-induced apoptosis, neuronal survival and cardiac development and angiogenesis. As part of the MAPK/ERK signaling pathway, acts as a negative regulator of apoptosis in cardiomyocytes via promotion of STUB1/CHIP-mediated ubiquitination and degradation of ICER-type isoforms of CREM (By similarity).
Synonyms: MEK5; PRKMK5; MAPKK5; HsT17454
Tractability: Small molecule: a structure with a bound ligand is known; a high-quality ligand is known; it belongs to a druggable protein family. PROTAC: it is named in the literature on targeted protein degradation; ubiquitination databases record sites on it; its protein half-life has been measured; a small molecule that binds it is known.
Target class: STE protein kinase group; Kinase; Enzyme; Protein Kinase; STE protein kinase STE7 family
Chemical probes: BIX-02188 (high quality), PLX-4720
Gene: Protein-coding gene on chromosome 15 (67,542,611 to 67,807,123, forward strand). Ensembl gene ENSG00000137764.
Subcellular location (Human Protein Atlas): Microtubules; Primary cilium; Basal body; Cytokinetic bridge; Nucleoli
Pathways (Reactome):
Signal Transduction: Signalling to ERK5
Gene Ontology:
Molecular function: protein binding; protein kinase activity; ATP binding; MAP kinase kinase activity; protein serine kinase activity; protein tyrosine kinase activity
Biological process: cellular response to growth factor stimulus; cellular response to laminar fluid shear stress; MAPK cascade; negative regulation of canonical NF-kappaB signal transduction; negative regulation of cell migration involved in sprouting angiogenesis; negative regulation of chemokine (C-X-C motif) ligand 2 production; negative regulation of extrinsic apoptotic signaling pathway in absence of ligand; negative regulation of heterotypic cell-cell adhesion; negative regulation of interleukin-8 production; negative regulation of response to cytokine stimulus; negative regulation of smooth muscle cell apoptotic process; negative regulation of transcription by RNA polymerase II; positive regulation of protein metabolic process; positive regulation of transcription by RNA polymerase II; signal transduction; ERK5 cascade; insulin-like growth factor receptor signaling pathway; positive regulation of cell growth; positive regulation of epithelial cell proliferation
Cellular component: spindle
Genetic constraint (gnomAD): Loss-of-function variants: 21 observed, 25.18 expected, observed/expected ratio (o/e) 0.83, 90% interval 0.59 to 1.2. The upper end of that interval is the gene's LOEUF score, 1.2, which puts it in group 5 of 6, group 1 being the genes least tolerant of losing a copy. Missense variants: 216 observed, 249.43 expected, observed/expected ratio (o/e) 0.87, 90% interval 0.77 to 0.97. Synonymous variants: 100 observed, 93.57 expected, observed/expected ratio (o/e) 1.07, 90% interval 0.91 to 1.26.
Homologues: Orthologues: chimpanzee MAP2K5 (100% identical), macaque MAP2K5 (99% identical), dog MAP2K5 (99% identical), rat Map2k5 (98% identical), mouse Map2k5 (98% identical), guinea pig MAP2K5 (98% identical), pig MAP2K5 (94% identical), rabbit MAP2K5 (93% identical), tropical clawed frog map2k5 (85% identical), zebrafish map2k5 (78% identical), Caenorhabditis elegans sek-5 (22% identical), Caenorhabditis elegans sek-4 (21% identical). Paralogues in human: MAP2K1 (34% identical), MAP2K2 (34% identical), MAP2K4 (29% identical), MAP2K7 (28% identical), MAP3K3 (23% identical), MAP3K2 (22% identical), MAP3K4 (22% identical), NEK1 (15% identical).
Diseases named in the same sentence as MAP2K5 in open-access papers:
MAP2K5 is named in the same sentence as 81 diseases in open-access papers, as found by Europe PMC text mining. Sharing a sentence is not in itself a finding about the gene and the disease. The quoted sentences say what the papers report.
breast cancer (26 papers, 2008 to 2025). A primary or metastatic malignant neoplasm involving the breast. "These included regulators of the RAS MAPK pathway, including SPRED1-encoding Spred-1 and MAP2K5, both of which are known to reduce tumor growth, although the latter promotes invasiveness in breast cancer." (PMID 38473331, 2024). "The mitogen-activated protein kinase kinase 5 (MEK5)/extracellular signal-regulated kinase 5 (ERK5) axis has been reported to promote tumorigenesis in breast cancer (BC)." (PMID 35609325, 2022).
Obesity (15 papers, 2012 to 2023). Accumulation of substantial excess body fat. "Since then, a number of studies have pinpointed that MAP2K5 rs2241423 is associated with both childhood and adulthood obesity in different Asian populations and Caucasian, which most results were consistent." (PMID 35368675, 2022). "This integrative genomics approach identifies four cis-eQTL-eGene relationships associated with BMI or obesity-related traits, including rs4776984 and MAP2K5, which we further confirm by EMSA, and highlights 38 additional candidate genes." (PMID 29666371, 2018). "The MAP2K5-linked single nucleotide polymorphism rs2241423 was associated with BMI and obesity in two cohorts of Swedish and Greek children, suggesting a role for MAP2K5 in early weight regulation." (PMID 23800102, 2013). "rs2241423 was associated with BMI and obesity in two independent European cohorts suggesting a role for MAP2K5 in early weight regulation." (PMID 22594783, 2012). "In this study we aim to further explore the association of the MAP2K5-linked SNP, rs2241423, to obesity and BMI in two cohorts of Swedish and Greek children." (PMID 22594783, 2012). "However, until now, no further study has been carried out to thoroughly delineate the association of variants within the MAP2K5 gene region with obesity." (PMID 35368675, 2022). "While the integration of our functional genomics datasets was able to resolve regions such as the MAP2K5 locus, where a single gene emerged as the likely target of the genetic association with obesity, we also uncovered unexpected complexities amongst other loci." (PMID 34489471, 2021). "Variations in the gene encoding the dual specificity mitogen-activated protein kinase kinase 5 (MAP2K5) were subsequently identified as risk factors for obesity in a meta-analysis of data from five cohorts of Chinese, Malay and Indian descent (total n = 10 482)." (PMID 22594783, 2012). "The results deepened our understanding of the adipogenesis of MAP2K5 throughout the whole genetic region and provided a possible target for future obesity intervention or therapy." (PMID 35368675, 2022). "Overall, the present study deepened our understanding of MAP2K5 adipogenesis throughout the whole genetic region and provided a possible target for future obesity intervention or therapy." (PMID 35368675, 2022). "All results revealed that rs7175517 of MAP2K5 was functionally correlated with obesity in both Chinese and United Kingdom populations." (PMID 35368675, 2022). "We identified the nominally significant associations with obesity for effect alleles of 6 SNPs at FTO, SEC16B, TFAP2B, RBJ, MAP2K5 and CDKAL1 (ORs for the effect allele ranged between 1.19 and 1.41, nominal two-sided P < 0.05)." (PMID 26800887, 2016). "We identified obesity association for 6 SNPs near SEC16B, RBJ, CDKAL1, TFAP2B, MAP2K5 and FTO (odds ratios (ORs) ranged from 1.19 to 1.41, nominal two-sided P-values < 0.05)." (PMID 26800887, 2016). "Novel functions of three other genes, FAIM2, MAP2K5, and TFAP2B, were also found to be associated with obesity development." (PMID 22355368, 2012). "For other cardiometabolic traits, the obesity predisposing locus, FTO-rs1558902 yielded significant association with systolic blood pressure (SBP) (P = 0.001), while the risk alleles of SNPs in/near GNPDA2, PCSK1 and MAP2K5 yielded nominal association with blood pressures (P < 0.05)." (PMID 29212175, 2017). "In summary, in our sample of Chinese children, we replicated eight adult East Asian obesity-related loci (in/near FTO, MC4R, GNPDA2, PCSK1, SEC16B, MAP2K5, ITIH4 and BDNF) in the same direction of effect as previous reports in adults." (PMID 29212175, 2017).
colon cancer (8 papers, 2012 to 2023). "FuSiOn identified ten kinases (BMP2K, DCLK3, LIMK2, MAP2K5/MEK5, MAP3K3/MEKK3, ROS1, SIK2, TAOK2, ULK1, and ULK2) whose depletion mimicked the phenotypic effect of p62 depletion in HCT116 colon cancer cells." (PMID 33101709, 2020).
lung carcinoma (6 papers, 2019 to 2024). "A network of interactions between proteins TUBB2B, MAPK7, TUBAL3, MAP2K5, and GJA1 (Cx43) suggests that reduced expression of MAPK and tubulin genes could be responsible for the attenuation of the gap junction pathway and insensitivity of lung cancer cells to cisplatin." (PMID 38351531, 2024).
atherosclerosis (4 papers, 2019 to 2025). A disease characterized by the build-up of fatty material and calcium deposition in the arterial wall resulting in partial or complete occlusion of the arterial lumen. "MAP2K5, a component of the MAPK/ERK5 signaling pathway that influences endothelial dysfunction and atherosclerosis, reached genome-wide significance in the LGF and strong comorbid signal (p-value = 3.1e-13) but showed only nominal evidence in CVD traits (p-value = 5.3e-03)." (PMID 41299637, 2025).
Hyperglycemia (2 papers, 2021 to 2022). An increased concentration of glucose in the blood. "Hyperglycemia inhibited hippocampal mitogen-activated protein kinase kinase 5 (MEK5) phosphorylation in TBI rats." (PMID 34176788, 2021). "Interestingly, hyperglycemia regulates microglia polarization into an increasingly proinflammatory subtype, which can be suppressed by sustained activation of ERK5 by transfected MAP2K5/MEK5." (PMID 36005139, 2022).
migraine (2 papers, 2020 to 2022). "Previous GWASs have identified six RLS risk loci (MEIS1, BTBD9, MAP2K5, PTPRD, TOX3, and an intergenic region on chromosome 2p14); however, only MEIS1 has been found to be associated with RLS in patients with migraine via candidate gene approach." (PMID 35350973, 2022).
osteoporosis (2 papers, 2017 to 2025). A condition of reduced bone mass, with decreased cortical thickness and a decrease in the number and size of the trabeculae of cancellous bone (but normal chemical composition), resulting in increased fracture incidence. "FMO4 and NOV were associated with a decreased risk of osteoporosis, whereas MAP2K5, PSMA4, SCARB1 and VEGFA were linked to an increased risk." (PMID 40764749, 2025).
ovarian carcinoma (2 papers, 2023 to 2025). A malignant neoplasm originating from the surface ovarian epithelium. "The function and relationships between ovarian cancer and other upregulated mRNA genes (PRKCA, HNF1A, and MAP2K5) are not clear and further investigation is necessary." (PMID 39592485, 2025).
restless legs syndrome (2 papers, 2021). A condition that occurs while resting or lying in bed; it is characterized by an irresistible urgency to move the legs to obtain relief from a strange and uncomfortable sensation in the legs. "In the central nervous system, some polymorphisms of MAP2K5 have been associated with restless legs syndrome/William–Ekbom disease (RLS/WED) and neuropsychologic disorders." (PMID 34168549, 2021).
small cell lung carcinoma (2 papers, 2020 to 2022). Small cell lung cancer (SCLC) is a highly aggressive malignant neoplasm, accounting for 10-15% of lung cancer cases, characterized byrapid growth, and early metastasis. "Moreover, MAPK7 and its upstream activator, MAP2K5, are also known to control lipid metabolism in small cell lung cancer cells." (PMID 36232834, 2022).
Alzheimer disease (1 paper, 2017). A progressive, neurodegenerative disease characterized by loss of function and death of nerve cells in several areas of the brain leading to loss of cognitive function such as memory and language. "The risk locus on chromosome 15q23 (encompassing MAP2K5 and SKOR1) overlaps with GWAS signals of four different traits, including the posterior cortical atrophy variant of Alzheimer's disease (appendix pp 39–41)." (PMID 29029846, 2017).
Anxiety (1 paper, 2023). Intense feelings of nervousness, tension, or panic often arise in response to interpersonal stresses. "Previous studies have found that MAP2K5 mRNA and its predicted miRNA are potentially important contributors to depression and anxiety-related characteristics." (PMID 36911124, 2023).
prostate tumors (1 paper, 2009). "MAP2K5 (MEK5) kinase has been shown to be correlated with metastasis in prostate tumors and has been involved in breast carcinogenesis." (PMID 19671193, 2009).
schizophrenia (1 paper, 2021). A major psychotic disorder characterized by abnormalities in the perception or expression of reality. "In addition, our Map2k5-deficient mouse model provides a unique tool to further investigate the role of the Map2k5–Erk5 pathway in other central nervous system disorders with dopamine deficits, such as schizophrenia." (PMID 34168549, 2021).
Sepsis (1 paper, 2025). Sepsis is defined as life-threatening organ dysfunction caused by a dysregulated host response to infection. "Likewise, serine/threonine kinases MAP2K5 and MAP3K1, both classified as Tier 1 targets, are integral components of the MAPK signaling cascade, orchestrating oxidative stress responses, inflammatory mediator release, and apoptosis during sepsis." (PMID 40761792, 2025). "Additionally, moderate colocalization evidence was observed for MAP2K5 (mitogen-activated protein kinase kinase 5), PIK3C2A (phosphatidylinositol-4-phosphate 3-kinase catalytic subunit type 2 alpha), and DSTYK (dual serine/threonine and tyrosine protein kinase) with sepsis outcomes (PPH4 > 0.5)." (PMID 40761792, 2025).
thyroid carcinoma (1 paper, 2021). "They performed functional studies in the human thyroid carcinoma cell line B–CPAP stably expressing MAP2K5 p.Ala321Thr or MAP2K5 p.Met367Thr." (PMID 33946592, 2021).
Tremor (1 paper, 2021). An unintentional, oscillating to-and-fro muscle movement about a joint axis. "In addition, SNPs of MAP2K5 have been shown to be associated with the reduced risk of RLS/WED, but increased the risk of tremor in PD (rs12593813, 61.0% vs. 46.5%, p = 0.001)." (PMID 34168549, 2021).
type 2 diabetes (1 paper, 2021). "Among the hub genes screened, four genes (NEUROG3, TCF7L2, MAP2K5 and RPTOR) were validated as showing the upregulated expression pattern in blood samples in type 2 diabetes cases." (PMID 34830198, 2021).
tumor (42 papers, 2007 to 2025). "Still, for the HABP2 gene recently indicated as tumor suppressor, and for the MAP2K5 gene, encoding a protein kinase that belongs to the MAP kinase family, a possible pathogenic role has been suggested." (PMID 33488516, 2020). "MAP2K5 activates MAPK7 that, in combination with MMP9, is associated with positive tumor-inducing signaling in cancer patients." (PMID 36552714, 2022). "Retroviral insertions were present in the mouse homologs of 10 genes tagged in the zebrafish tumor samples: Brd2, Cirbp, Fgf8, Hexim1, Map2k5, Mmp14, Ncoa2, Slc30a5, Sox4, and Sox5." (PMID 21533036, 2011). "This highly refined list of selection candidates, which contains genes related to muscle metabolism and angiogenesis (MYOF, MAP2K5) and tumor suppression (MCC), yields valuable insight for future examination of adaptation in both Mongolian and Tibetan ethnic groups." (PMID 23874230, 2013).
cancer (40 papers, 2007 to 2025). A tumor composed of atypical neoplastic, often pleomorphic cells that invade other tissues. "MAP2K5 (mitogen-activated protein kinase kinase 5, also known as MEK5) has been associated with various diseases including cardiovascular diseases, cancers, and central nervous system disorders." (PMID 34168549, 2021). "Although the role of Map2k5-Erk5 in cardiovascular diseases and cancer has been mostly clarified, the molecular mechanism of Map2k5 in the central nervous system remained largely unknown." (PMID 34168549, 2021). "Cytoscape analysis of gene network revealed important cancer pathways including hub genes at NFGR, MAPK3, and SMAD7 for OS, and hub genes at FOXP1, MAP2K5, FGFR1, and NOTCH2 for DFS." (PMID 31608231, 2019). "Because of the involvement of MAP2K5/MAPK7 in angiogenesis, the epithelial-mesenchymal transition, and diverse oncogenic pathways, the role of MAP2K5/MAPK7 in cancer has been the subject of intense investigation for the last decade." (PMID 28596290, 2017).
central nervous system disorder (1 paper, 2021). A disease involving the central nervous system. "MAP2K5, a member of the MAPK family, is associated with central nervous system disorders." (PMID 34168549, 2021).
neurological disorder (1 paper, 2021). "Based on the finding that polymorphisms (rs12593813, rs11635424, and rs868036) in MAP2K5 were associated with a reduced risk of RLS/WED, a neurological disorder characterized by dopamine and iron dysfunction, we established a targeted deletion of Map2k5 in mice." (PMID 34168549, 2021).
MAP2K5 also shares sentences with these, for which no sentence is quoted: prostate carcinoma (11 papers); melanoma (9); infection (6); adenocarcinoma (4); cardiac hypertrophy (4); adenoma (3); cardiovascular diseases (3); colorectal cancer (3); endothelial dysfunction (3); hepatocellular carcinoma (3); triple-negative breast carcinoma (3); breast tumors (2); chronic myelogenous leukemia (2); colon adenoma (2); diabetes (2); lung adenocarcinoma (2); metastatic prostate carcinoma (2); neuroblastoma (2); and Muscular Disorder (1); asthma (1); autoimmune disease (1); Behçet’s disease (1); cervical cancer (1); Cirrhosis (1); colon adenocarcinoma (1); colorectal adenocarcinoma (1); colorectal adenoma (1); Crohn disease (1); depression (1); diabetic cardiomyopathy (1).
A further 28 diseases each share a sentence with MAP2K5 in 1 paper.